OXR1 (oxidation resistance 1)
Description:
Inhibits the activity of the vacuolar-type ATPase (V-ATPase) by inducing disassembly of the V-ATPase complex. Protects the Golgi apparatus lumen from excess acidification by inhibiting V-ATPase ATP hydrolytic activity through interaction with V-ATPase catalytic subunit ATP6V1A, maintaining optimal conditions for glycosylation enzymes (By similarity). Involved in protection from oxidative damage. Protects neuronal cells from oxidative stress (By similarity).
Synonyms: Nbla00307; TLDC3; CHEGDD
Tractability: PROTAC: ubiquitination databases record sites on it; its protein half-life has been measured.
Gene: Protein-coding gene on chromosome 8 (106,270,144 to 106,752,694, forward strand). Ensembl gene ENSG00000164830.
Subcellular location: Mitochondrion; Nucleus, nucleolus; Golgi apparatus, cis-Golgi network membrane; Golgi apparatus, trans-Golgi network membrane
Subcellular location (Human Protein Atlas): Vesicles
Gene Ontology:
Biological process: response to oxidative stress
Cellular component: mitochondrion; nucleus; Golgi apparatus; nucleolus
Genetic constraint (gnomAD): Loss-of-function variants: 11 observed, 37.77 expected, observed/expected ratio (o/e) 0.29, 90% interval 0.18 to 0.48. The upper end of that interval is the gene's LOEUF score, 0.48, which puts it in group 2 of 6, group 1 being the genes least tolerant of losing a copy. Missense variants: 491 observed, 520.87 expected, observed/expected ratio (o/e) 0.94, 90% interval 0.88 to 1.02. Synonymous variants: 151 observed, 177.75 expected, observed/expected ratio (o/e) 0.85, 90% interval 0.74 to 0.97.
Homologues: Orthologues: macaque OXR1 (97% identical), chimpanzee OXR1 (94% identical), pig OXR1 (90% identical), rabbit OXR1 (90% identical), dog OXR1 (90% identical), rat Oxr1 (85% identical), mouse Oxr1 (84% identical), guinea pig OXR1 (82% identical), tropical clawed frog oxr1 (68% identical), zebrafish oxr1b (58% identical). Paralogues in human: NCOA7 (39% identical), TLDC2 (12% identical), MEAK7 (11% identical).
Diseases named in the same sentence as OXR1 in open-access papers:
OXR1 is named in the same sentence as 58 diseases in open-access papers, as found by Europe PMC text mining. Sharing a sentence is not in itself a finding about the gene and the disease. The quoted sentences say what the papers report.
amyotrophic lateral sclerosis (8 papers, 2011 to 2024). Amyotrophic lateral sclerosis (ALS) is a neurodegenerative disease characterized by progressive muscular paralysis reflecting degeneration of motor neurons in the primary motor cortex, corticospinal tracts, brainstem and spinal cord. "Oxidation resistance 1 (OXR1) has been shown previously to be critical for oxidative stress resistance in neuronal cells; deletion of this gene causes neurodegeneration in mice, yet conversely, overexpression of OXR1 is protective in cellular and mouse models of amyotrophic lateral sclerosis." (PMID 26668325, 2016). "In fact, it was demonstrated that OXR1 plays a protective role in oxygen-induced retinopathy, diabetic retinopathy, Parkinson’s disease, ischemia-induced neuronal damage, and amyotrophic lateral sclerosis (ALS)." (PMID 37958785, 2023). "OXR1 has been implicated in a growing list of neurodegenerative diseases such as oxygen-induced retinopathy, diabetic retinopathy, Parkinson’s disease, ischemia-induced neuronal damage, and amyotrophic lateral sclerosis (ALS)." (PMID 33384581, 2020). "Oxidation resistance 1 (OXR1) can protect against OS in cellular and mouse models of amyotrophic lateral sclerosis (ALS) when over-expressed, whereas deletion of Oxr1 in mice causes neurodegeneration." (PMID 27036366, 2016). "Recently, oxidation resistance 1 (OXR1) has emerged as a critical regulator of neuronal survival in response to oxidative stress, and is upregulated in the spinal cord of patients with amyotrophic lateral sclerosis." (PMID 25753484, 2015). "These authors also report that OXR1 is overexpressed in amyotrophic lateral sclerosis (ALS) patients and in mouse models of ALS, indicating a possible protective function of OXR1 in this neurodegenerative disorder." (PMID 22873401, 2012). "We have also demonstrated that an Oxr1 transgene can delay neurodegeneration in an mouse model of amyotrophic lateral sclerosis (ALS), and over-expressing Oxr1 in mammalian cells can alleviate cellular abnormalities caused by pathogenic ALS-associated mutations." (PMID 27036366, 2016). "Finally we show up-regulation of Oxr1 in both human and pre-symptomatic mouse models of amyotrophic lateral sclerosis, indicating that Oxr1 is potentially a novel neuroprotective factor in neurodegenerative disease." (PMID 22028674, 2011). "Here, we tested the hypothesis that OXR1 is a key neuroprotective factor during amyotrophic lateral sclerosis pathogenesis by crossing a new transgenic mouse line that overexpresses OXR1 in neurons with the SOD1G93A mouse model of amyotrophic lateral sclerosis." (PMID 25753484, 2015). "Taken together, these data identify OXR1 as the first neuron-specific antioxidant modulator of pathogenesis and disease progression in SOD1-mediated amyotrophic lateral sclerosis, and suggest that OXR1 may serve as a novel target for future therapeutic strategies." (PMID 25753484, 2015).
Ataxia (7 papers, 2011 to 2025). Ataxia refers to impaired coordination of voluntary muscle movement. "The neuroprotective function associated with PGI-1 has also been documented in an animal model of ataxia, modulating the neuroprotective properties of oxidation resistance protein 1 (Oxr1), a key player in the regulation of oxidative stress and glucose metabolism in the brain." (PMID 39904372, 2025). "Importantly, Oxr1tm1a/tm1a mutants displayed progressive cerebellar degeneration and ataxia to the same degree as the original homozygous Oxr1 deletion mutants and over an identical timescale." (PMID 26668325, 2016). "Next, we generate a ubiquitous, adult inducible knockout of Oxr1 that surprisingly displays rapid-onset ataxia and cerebellar neurodegeneration, establishing for the first time that the distinctive pathology associated with the loss of Oxr1 occurs irrespective of developmental stage." (PMID 38929124, 2024). "Animals of this genotype displayed no ataxia or growth defects, and no cell death was detected in any region of the brain, including the cerebellar GCL, compared to littermates that did not contain the Oxr1 transgene (bel/bel; Tg(CAG-Oxr1)−/−)." (PMID 22028674, 2011).
Parkinson disease (4 papers, 2016 to 2025). A progressive degenerative disorder of the central nervous system characterized by loss of dopamine producing neurons in the substantia nigra and the presence of Lewy bodies in the substantia nigra and locus coeruleus. "A separate study pointed out that OXR1 depletion aggravated neurodegenerative disorders in Parkinson’s disease." (PMID 40429980, 2025). "The Parkinson’s and ALS mouse models further demonstrate that increasing OXR1 expression alleviates physical symptoms associated with neurodegeneration." (PMID 33384581, 2020). "They demonstrated that an increased level of the OXR1-targeting microRNA miR-137 is found in exosomes in serum of Parkinson’s patients compared to controls." (PMID 33384581, 2020). "In all cell types OXR1 mRNA levels were lower in the Parkinson’s groups compared to matched controls." (PMID 33384581, 2020). "Oxr1 controls sensitivity to oxidative stress and as such, the absence of Oxr1 in dopaminergic synapses might confer susceptibility to oxidative damage (e.g., during Parkinson’s disease)." (PMID 37918396, 2023). "Interestingly, the deregulation of the TLDc family has been demonstrated in several disease states, including an increase in OXR1 protein expression in end-stage ALS spinal cord biopsies and a reduction in OXR1 in the posterior cingulate cortex of patients with Parkinson disease." (PMID 26668325, 2016).
Alzheimer disease (3 papers, 2023 to 2024). A progressive, neurodegenerative disease characterized by loss of function and death of nerve cells in several areas of the brain leading to loss of cognitive function such as memory and language. "However, the treatment of Alzheimer’s disease mouse models with OXR1 and OXR2 antagonists elicits contradictory effects on memory performances so far44,45." (PMID 39433837, 2024). "Briefly considering common disease themes between Alzheimer’s disease and the ALS-Ox subtype, expression of oxidation-associated transcripts COX4I2, NDUFA4L2, and OXR1 is consistent with reported literature, although CP is known to be upregulated in Alzheimer’s55." (PMID 36609402, 2023).
Anxiety (3 papers, 2021 to 2024). Intense feelings of nervousness, tension, or panic often arise in response to interpersonal stresses. "Although a majority of the anxiety and depression studies focused on OXR1, there was accumulating evidence suggesting OXR2 activity is anxiolytic." (PMID 34942932, 2021). "Based on the results obtained in animals, it might be interesting to investigate the role of pharmacological modulation of OXR1 in reducing anxiety and depression traits in migraine patients." (PMID 38397400, 2024). "OXR1 in the amygdala might increase anxiety in No-LH rats, and the enhanced vigilance might be beneficial for coping with stressful situations." (PMID 34942932, 2021).
depression (3 papers, 2021 to 2024). "An orexin genotype study of patients with depression revealed that a polymorphism (Ile408Val) in the OXR1 gene HCRTR1 significantly differed between cases and controls." (PMID 34942932, 2021). "Genetic studies using OXR1 knockout mice have also demonstrated a decrease in depression-like behavior in the FST and tail suspension test, whereas OXR2 knockout animals displayed increased behavioral despair." (PMID 34942932, 2021). "Orexin peptides, orexin receptor 1 (OXR1) and 2 (OXR2) in brain areas involved in major depression and serum OX-A and corticosterone (CORT) concentrations were quantified and compared between rat groups." (PMID 34942932, 2021). "To further understand differences in the orexin system between LH and No-LH rats, we quantified the OX-A, OX-B, OXR1, and OXR2 protein levels in the brain areas involved in major depression." (PMID 34942932, 2021).
diabetic retinopathy (3 papers, 2016 to 2023). "A subsequent study of diabetic retinopathy more clearly demonstrates a causal effect of OXR1 in retinal degeneration." (PMID 33384581, 2020). "In diabetic retinopathy, miR-200b targets OXR1, inducing a decrease in both OXR1 mRNA and protein and exacerbating oxidative damage." (PMID 37958785, 2023). "Furthermore, the therapeutic use of Oxr1 has also been tested successfully in a model of diabetic retinopathy and in kidneys of a nephritis mouse model using Oxr1-overexpressing mesenchymal stem cells." (PMID 26668325, 2016).
lupus nephritis (3 papers, 2014 to 2019). Glomerulonephritis in the context of systemic lupus erythematosus. "We then tested the in vivo effects of OXR1-MSCs in mice suffering from acute anti-GBM disease or spontaneous lupus nephritis, both diseases involved in renal oxidative damage." (PMID 25995969, 2014). "Collectively, the findings of this study indicate that OXR1 and oxidative stress are critical players in the pathogenesis and progression of lupus nephritis, in both acute anti-GBM nephritis and chronic lupus nephritis." (PMID 25995969, 2014). "In this study, we investigated the potential influence of a key antioxidant gene, oxidation resistance 1, on inflammatory damage and oxidative stress in lupus nephritis and anti-GBM induced disease and its therapeutic potential." (PMID 25995969, 2014). "The second is that the testing of human OXR1 will make it more feasible to be translated for treatment of human lupus nephritis if proved to be effective in mouse study." (PMID 25995969, 2014). "Delivering the oxidation resistance-1 (OXR1) gene to mouse kidneys by genetic manipulation can protect the kidney from damage induced by serum nephrotoxic agents, and prevent the animal from developing lupus nephritis." (PMID 31635056, 2019). "The anti-apoptosis impact of OXR1 may have resulted in longer-surviving MSCs, and this may have contributed in part to the beneficial impact on lupus nephritis." (PMID 25995969, 2014). "Over-expression of Oxr1 in vivo delays neurodegenerative phenotypes driven by a reduction in OS levels and inflammation and intravenous delivery of stably transfected human OXR1 in MSCs resulted in a reduction of OS and inflammation in a mouse model of lupus nephritis." (PMID 28707022, 2017). "Our data indicated that OXR1-MSCs exhibited significant protective effects on both anti-GBM induced renal injury and spontaneous lupus nephritis, compared with control MSCs." (PMID 25995969, 2014). "Hence, in this study, we investigated the impact of OXR1 on suppressing oxidative damage in experimentally induced anti-GBM nephritis, and spontaneously arising lupus nephritis." (PMID 25995969, 2014). "OXR1 was highly expressed in kidneys in mice with spontaneous lupus nephritis, but not in healthy B6 mouse." (PMID 25995969, 2014).
brain ischemia (2 papers, 2020 to 2022). Diminished or absent blood supply to the brain caused by obstruction (thrombosis or embolism) of an artery resulting in neurologic damage. "Likewise, a continuous decline of OXA level in CSF and a rise of expression of OXR1 in the cortical region was discovered in patients with cerebral ischemia, suggesting an involvement of the orexin system in an ischemic insult." (PMID 36619670, 2022). "Irving observed an increase of OXR1 mRNA but not OXR2 mRNA in rat model of brain ischemia." (PMID 32539736, 2020).
developmental delay (2 papers, 2021 to 2023). "We report a novel loss-of-function mutation in the TLDc domain of the human OXR1 gene, resulting in early-onset epilepsy, developmental delay, cognitive disabilities, and cerebellar atrophy." (PMID 37773136, 2023). "We reported a de novo mutation within the critical TLDc domain of OXR1 leading to exon skipping, protein depletion (OXR1ΔEx18) and a severe early-onset syndrome characterized by epilepsy, global developmental delay, cognitive disabilities, and cerebellar atrophy." (PMID 37773136, 2023).
dyslexia (2 papers, 2017 to 2024). A learning disorder characterized by an impairment in processing written words. "One validated stop-gain, very near the start of the OXR1 gene (NM_001198534:p.W5X, NM_001198535:p.W5X), was found in three children from a family, two affected by SLI necessitating special educational needs and a third with a diagnosis of dyslexia." (PMID 28440294, 2017).
insomnia (2 papers, 2018 to 2022). A sleep disorder characterized by difficulty in falling asleep and/or remaining asleep. "This function of OX has recently been targeted for treatment of insomnia with suvorexant, a dual antagonist of OXR1 and OXR2." (PMID 30618563, 2018).
Lupus- (2 papers, 2014 to 2020). "Increasing OXR1 expression has also been shown to delay Lupus-associated induced kidney failure, which is associated with oxidative stress, suggesting OXR1 may have therapeutic applications beyond treating neurodegenerative diseases." (PMID 33384581, 2020). "OXR1 expression was detected in kidneys of different strains of mice, including B6, and murine model of lupus model mice (B6.Sle1." (PMID 25995969, 2014). "Collectively, these findings indicate that OXR1 resets the oxidative imbalance in lupus." (PMID 25995969, 2014).
metabolic syndrome (2 papers, 2013 to 2022). A cluster of metabolic risk factors for CARDIOVASCULAR DISEASES and TYPE 2 DIABETES MELLITUS. "Here we investigated the effects of chronic treatment with the novel selective OXR-1 antagonist ACT-335827 in a rat model of diet-induced obesity (DIO) associated with metabolic syndrome (MetS)." (PMID 24416020, 2013).
nephritis (2 papers, 2014 to 2016). Inflammation of renal tissue. "We found that the anti-oxidant gene, oxidation resistance 1 gene (OXR1) was significantly up-regulated in kidneys of nephritis resistant mice (B6, BALB/c) compared with the sensitive mice (DAB1, 129/svj, NZW)." (PMID 25995969, 2014). "We utilized mesenchymal stem cells (MSCs) as vehicles to carry OXR1 into the injured kidneys of nephritis model mice and investigated the influence of OXR1 on glomerulonephritis." (PMID 25995969, 2014). "OXR1-MSCs transplantation may exert a certain protective effect on nephritis by suppressing inflammation and oxidative stress." (PMID 25995969, 2014). "More importantly, OXR1-MSC transfer had a significant impact on redox balance, pro-inflammatory cytokine/chemokine production and infiltration of leukocytes into nephritis kidneys." (PMID 25995969, 2014).
Cerebellar atrophy (1 paper, 2023). Cerebellar atrophy is defined as a cerebellum with initially normal structures, in a posterior fossa with normal size, which displays enlarged fissures (interfolial spaces) in comparison to the foliae secondary to loss of tissue. "In 2019, it was reported that five patients from three families who carried four biallelic loss-of-function OXR1 variants were associated with cerebellar atrophy." (PMID 37773136, 2023). "Altogether, we presented the first evidence of molecular neuropathology underlying OXR1 deficiency associated cerebellar atrophy, neurodevelopmental impairment, and increased susceptibility to oxidative stress." (PMID 37773136, 2023). "In 2019, five patients from three families carrying four biallelic loss-of-function variants in OXR1 were reported to be associated with cerebellar atrophy." (PMID 37773136, 2023).
cervical cancer (1 paper, 2017). A primary or metastatic malignant neoplasm involving the cervix. "Next, to dissect the pathway(s) downstream of OXR1 in more detail, transcriptomic analysis was carried out in the human cervical cancer (HeLa) cell line in which the level of OXR1 was knocked-down by 85%." (PMID 28707022, 2017).
childhood asthma (1 paper, 2013). "We used an informative graph for oxidative stress derived from Gene Ontology and identified several variants in ERBB4, OXR1, and BCL2 with strong evidence for associations with childhood asthma." (PMID 24152222, 2013).
clear cell renal cell carcinoma (1 paper, 2017). "Moreover, higher OXR1 promoter methylation levels associate with clear cell renal cell carcinoma nuclear grade, a surrogate for tumor aggressiveness." (PMID 28662726, 2017). "A panel including OXR1 and MST1R promoter methylation allows specific and sensitive identification of renal cell tumors, and, especially, of clear cell renal cell carcinoma." (PMID 28662726, 2017). "A two-gene methylation panel comprising OXR1 and MST1R identified malignancy with 98% sensitivity and 100% specificity, and clear cell renal cell carcinoma with 90% sensitivity and 98% specificity." (PMID 28662726, 2017).
esophageal squamous cell carcinoma (1 paper, 2022). Esophageal squamous cell carcinoma (ESCC) is a type of esophageal carcinoma (EC) that can affect any part of the esophagus, but is usually located in the upper or middle third. "miR-373-3p targeting LATS2 and OXR1 enhances esophageal squamous cell carcinoma progression, and its expression was vigorously attenuated in the serum of patients with tumor resection." (PMID 34983307, 2022).
hearing loss (1 paper, 2016). "OXR1 contains the Tre2/Bub2/Cdc16 (TBC), lysin motif (LysM), domain catalytic (TLDc) domain, a motif present in a family of proteins including TBC1 domain family member 24 (TBC1D24), a protein mutated in a range of disorders characterized by seizures, hearing loss, and neurodegeneration." (PMID 26668325, 2016).
Hepatic fibrosis (1 paper, 2021). The presence of excessive fibrous connective tissue in the liver. "In addition, up-regulation of genes involved in tissue injury and hepatic fibrosis (Adora1), caspase-dependent apoptosis (Moap1), and oxidative stress and antioxidant defense (Ephx2 and Oxr1) was identified only in the liver treated with Zn ions." (PMID 33567653, 2021).